IL2 (interleukin 2)
Diseases named in the same sentence as IL2 in open-access papers (continued):
Sharing a sentence is not in itself a finding about the gene and the disease.
melanoma (continued). "Outpatient staccato pulse intravenous Interleukin-2 has activity in melanoma." (PMID 30400822, 2018). "A data series of 274 patients with BRAF-mutated melanoma who sequentially received BRAF inhibitors and immunotherapy (high-dose IL-2, ipilimumab, or PD-1 inhibitors) illustrated that ipilimumab therapy after BRAF inhibitors was associated with no tumor response and poor survival." (PMID 29848375, 2018). "TIL therapies in melanoma have shown response rates of up to 50% in contrast to previously FDA approved therapies such as interleukin-2 with response rates near 15% at best, and melanoma patients with the highest neoantigen load have the best progression-free survival." (PMID 30140266, 2018). "We hypothesize that the drug uptake in CEA− tumors is primarily caused by CEA-IL2v binding to IL-2 receptor present on tumor infiltrating lymphocytes similarly to what has been reported for IL-2 therapy in melanoma, head and neck- and renal cell carcinoma." (PMID 29872502, 2018). "Besides its application in melanoma and renal cell carcinoma, the possibility of IL-2 utilization in other solid tumor types was tested." (PMID 28927416, 2017). "In addition to B16F10 melanoma, the efficacy of IL-2-Fc-fusion proteins was also investigated in the CT26 colorectal carcinoma syngeneic tumour model." (PMID 28497796, 2017). "In the current landscape, superior response rates observed with BRAF/MEK inhibitors and PD-1/CTLA-4 inhibitors have resulted in these agents supplanting HD IL-2 in the treatment of melanoma patients; particularly when coupled with the attendant complexities of HD IL-2 administration." (PMID 28923120, 2017). "In this study, we in vitro generated IL-2 and IL-7 effectors derived from congenic mice and assessed vulnerability of IL-2 and IL-7 effectors to Treg cells in vitro, and then in vivo in a mouse model of subcutaneous tumor, B16 melanoma that provides an in vivo Treg-cell-enriched environment." (PMID 28496990, 2017). "However, intriguingly, these experiments also revealed that both IL-23XFc and IL-2/mAb were in fact less effective than the parental IL-2WTFc protein in the B16F10 melanoma model." (PMID 28497796, 2017). "Furthermore, ABCB5+ melanoma cells inhibit T-cell activation through IL-2 and induce CD4+CD25+FoxP3+ regulatory T (Treg) cells via B7.2 dependent manner." (PMID 28137308, 2017). "As IL-2 complex was administered to our melanoma tumor-bearing mice to support the infused CAL-101 T cells, we suspected that this cytokine was important for the engraftment of these infused cells and could compensate for IL-7." (PMID 29033940, 2017). "In regard of this, immunotherapy (IFN-α and IL-2) and oncolytic virotherapy that are not heavily dependent on genetic heterogeneity of melanoma would circumvent limitations associated with targeted therapies that target specific gene mutations." (PMID 28567163, 2017). "Additionally, pretreatment neutrophil and total leukocyte count were predictive of shorter overall survival in melanoma patients undergoing IL-2 treatment." (PMID 28239396, 2017). "Hitherto, high-dose interleukin-2 (HD IL-2) was the only approved immunotherapy for stage IV melanoma - based on durable long-term survival observed in a fraction of patients initially reported in a phase II study in 1994, further updated in a meta-analysis of phase II trials published in 1999." (PMID 28923120, 2017). "STAT1 activation in response to IL-2 also showed an age-related decline in melanoma patients not linked to tumor burden indicating a premature loss of NK cell function." (PMID 27153543, 2016). "The anti-tumor activity in vivo of IL2-GMCSF was evaluated in the melanoma model." (PMID 26850448, 2016). "Since there was about 11-fold reduction in IFN-γ release while only 3-fold reduction in IL-6 secretion were observed, this indicated that a lack of IFN-γ production may be the major defect in PBMC from melanoma patients in response to HD IL-2." (PMID 27153543, 2016).
melanoma (continued). "Prior therapy may have an impact on outcome of mRCC patients subsequently treated with HD IL-2, compared with melanoma patients." (PMID 27714434, 2016). "Therefore, α-CD137/α-PD-1 therapy outperformed the capacity α-CTLA-4/α-PD-1 or IL-2 treatment to synergize with SBRT in this mouse model, even though IL-2 in combination with SBRT-induced anti-tumor responses in human melanoma patients." (PMID 27160390, 2016). "Together, IL2-GMCSF fusion protein displayed strong anti-tumor effects in melanoma animal model." (PMID 26850448, 2016). "This further suggests that an intrinsic IFN signaling defect could contribute to a poor responsiveness to IL-2 in melanoma patients." (PMID 27153543, 2016). "In addition, in a model using murine B16 melanoma cells that were transfected to secrete IL-21, it was shown that local presence of IL-21 can also promote anti-tumor immunity by preventing IL-2-mediated Treg induction." (PMID 27656185, 2016). "HD IL-2 remains a viable treatment in melanoma and may be safely administered following progression on ipilimumab." (PMID 27660706, 2016). "Similar effect was also previously observed by another group using HD IL2 in malignant melanoma." (PMID 27777776, 2016). "Thus, the decreased pSTAT1 response to IL-2 represents a growing abnormal effector response in melanoma patients separate from a proliferative response induced by IL-2." (PMID 27153543, 2016). "Studies in a B16 melanoma model have shown that immunotherapy with an IL-2/anti-IL-2 mAb complex only binding to the IL-2βγ receptor abrogated IL-2 therapy mediated side effects (pulmonary edema) and led to a vigorous activation of cytotoxic immune cells with strong antitumor reactivity." (PMID 26220086, 2015). "However, IL-2 immunotherapy has emerged as first-line therapy for stage IV melanoma in patients with good performance status and eligibility per institutional guidelines." (PMID 25815245, 2015). "Finkelstein and colleagues reported that high DC/MDSC ratios and low pretreatment MDSC levels could predict response to high-dose IL-2 therapy in patients with melanoma and renal cell carcinoma." (PMID 25592374, 2015). "In an effort to better define characteristics of patients who may benefit from IL-2 therapy, Phan and colleagues retrospectively reviewed their experience of 374 patients with stage IV melanoma who were treated with high-dose IL-2 from 1988 – 1999." (PMID 25932372, 2015). "In melanoma, it has been shown that numerous tumor antigen-specific T cells can be isolated from excised material of a tumor mass, dissociating cells into single cell suspensions and adding the T-cell growth factor interleukin-2 (IL-2)." (PMID 26217587, 2015). "Lastly, interleukin-2 (IL-2) stimulates the growth, differentiation and survival of antigen-specific T-cells and has been used as monotherapy for several different cancer types, including melanoma." (PMID 26107883, 2015). "High-dose IL-2 is a chance for cure for patients with metastatic renal cell carcinoma or melanoma." (PMID 26557408, 2015). "For instance, a series of studies collectively involving 93 patients with stage IV melanoma were treated with the adoptive transfer of autologous TILs administered in conjunction with IL-2 following a lymphodepleting preparative regimen on three clinical trials." (PMID 26217587, 2015). "The Celis laboratory found that IL-2/anti-IL-2 antibody complexes (when combined with vaccination) could eradicate melanoma in mice receiving tumor-specific CD8+ T cells." (PMID 26101781, 2015). "IL-2 should remain part of the treatment paradigm in selected patients with melanoma and RCC." (PMID 24855563, 2014). "Six patients with melanoma received ipilimumab and 3 received vemurafenib before IL-2." (PMID 24855563, 2014).
melanoma (continued). "The use of high-dose bolus IL-2 remains limited because of its toxicity and relatively low response rates; however, the durable responses are clinically meaningful and IL-2 has a place in recently published treatment guidelines for both melanoma and renal cancer." (PMID 24855563, 2014). "The reasons for lack of response to IL-2 are starting to emerge: a recent study found that the T cell subset most induced by IL-2 in melanoma patients is regulatory T cells (Treg) expressing positive for CD4, CD25, Foxp3 and the inducible T cell costimulator (ICOS)." (PMID 24743024, 2014). "Interestingly, all studies described so far were done in the presence of IL-2, in part, in combination with other stimuli like FO-1 melanoma cells, T-cell depleted PBMC, or irradiated feeder cells together with phytohaemagglutinin." (PMID 24876666, 2014). "IL-2 has been used with meager success for both melanoma and renal cell carcinoma." (PMID 25506582, 2014). "Our retrospective study suggests that responding patients with melanoma have enhanced long-term responses if they receive >4 IL-2 cycles; however, 4 cycles may be sufficient in patients with RCC." (PMID 24855563, 2014). "Additionally, activation of co-stimulatory molecules (CD80, CD86, CD137), exogenous cytokine administration (interleukin-2, interferon-γ), and blockade of tumor angiogenesis can inhibit melanoma progression when combined with GM-CSF–expressing vaccines." (PMID 24971166, 2014). "In patients, NK cells exhibit phenotypic defects that may alter their function in vivo but these cells remain responsive to IL-2 activation, acquiring high lytic capacities towards melanoma cells." (PMID 24204708, 2013). "A retrospective review was performed on patients with stable melanoma brain metastases treated with HD IL-2 therapy (720,000 IU/kg per dose intravenously; 14 doses, 2 cycles per course, maximum 2 courses) from January 1999 to June 2011 at Saint Louis University." (PMID 23762555, 2013). "However, several reports in the literature have shown that HIV and melanoma patients treated with IL2, experience an increase in CD4+ CD25+ FoxP3+ regulatory T cells, which typically mediate natural immune tolerance." (PMID 24376444, 2013). "Twenty six percent of melanoma patients responded to IL2 based immunotherapy, developed vitiligo suggesting that antimelanotic T-cells which might be responsible for melanoma regression may also be linked to the destruction of normal melanocytes in vitiligo." (PMID 24312346, 2013). "The literature is limited regarding the use of HD IL-2 in patients with melanoma brain metastases." (PMID 23762555, 2013). "From these data, it may be suggested that Foxp3 participates in melanoma growth, the modulation of the IL-2, IFN-γ and TNF-α cytokines and CD25 expression, and that it also plays a possible role in immunosuppression." (PMID 24179494, 2013). "Pre-treatment with IL-27 resulted in lower IL-2 production in the co-culture that was specifically reversed by addition of an anti-PD-L1 neutralizing Ab, indicating that PD-L1 induction by IL-27 on melanoma cells decreased T-cell activation as expected." (PMID 24130734, 2013). "Interestingly, it seemed that a higher number of IDO responses were detected among melanoma patients that had received more immune-related treatments (i.e. IL-2, IFNα)." (PMID 22539948, 2012). "However, recent publications indicate that increased FOXP3 expression in CD8+ T cell serves as a good prognosis marker in melanoma patients undergoing high does IL-2 combined with peptide vaccination therapy." (PMID 22911710, 2012). "Thus ch14.18-IL2 induces far more potent antitumor effects in melanoma or NBL-bearing mice than the combination of ch14.18 mAb + IL2, and functions both as a T cell inducing vaccine and a potent activator of NK- mediated ADCC." (PMID 24634778, 2012).
melanoma (continued). "Importantly, prior studies by our group have shown that the FLLL32 analog does not induce apoptosis of PBMCs or NK cells cultured in the presence of IL-2 despite its potent direct effects on melanoma cells." (PMID 22899991, 2012). "Also, the addition of IL-2 to cyclophosphamide therapy reversed the growth inhibitory effects of cyclophosphamide on B16 melanoma cells and decreased survival time, compared with treatment with cyclophosphamide alone." (PMID 20953429, 2011). "In order to reduce the IL-2-related side effects, a variety of modifications to the high-dose IL-2 regimens have been tested in patients with melanoma, including alterations of dose, schedule and route, as well as chemical alterations of IL-2 molecular structure that alter its cellular targets." (PMID 24213115, 2011). "Taken together, these studies suggest that DAB/IL2 may have clinical utility for the treatment of melanoma." (PMID 22165955, 2011). "They showed that only 0.1% of melanoma cells could generate secondary tumors in NOD/SCID mice, whereas the melanoma-initiating cell fraction was 25% in NOD/SCID/IL-2−/− mice." (PMID 24212782, 2011). "Adoptive transfers of low numbers of naïve TRP-1-specific T cells into wild-type mice results in overt vitiligo and potent rejection of established B16 melanoma when given in combination with vaccine and IL-2, irradiation and anti-CTLA-4, or in lymphopenic hosts." (PMID 21911918, 2011). "A defined polymorphism in the CCR5 gene (CCR5Δ32) was associated with decreased survival following IL-2 administration in patients with Stage IV melanoma compared to patients not carrying the deletion." (PMID 24213115, 2011). "Interestingly, they also observed that sera obtained from patients with advanced melanoma inhibited IL-2-dependent STAT activation of normal donor's T cells, and a neutralizing monoclonal antibody to TGF-β1 counteracted such inhibition." (PMID 21875439, 2011). "The finding that partial responses to DAB/IL2 were associated with longer overall survival provides preliminary rationale for clinical trials in which patients are randomized to DAB/IL2 or FDA-approved agents for stage IV melanoma (i.e. IL-2, dacarbazine, ipilimumab or vemurafenib)." (PMID 22165955, 2011). "The administration of IL-2 activates endogenous antitumor reactive T cells and NK cells resulting in a 20%–30% objective response rate, with complete regression in only 5%–8% of the melanoma patients." (PMID 21234353, 2010). "We found that replacement of the CMV enhancer promoter with the TETP allowed tight melanoma-specific transgene expression, as IL-2 expression levels amounted to a minimal 149-fold to a maximal 5652-fold higher expression levels in melanoma cells compared to HeLa cells." (PMID 20670430, 2010). "In conclusion, we have demonstrated that T cell depletion with DAB/IL2 in melanoma patients is followed by a T cell repopulation of the peripheral blood, the de novo appearance of CD8+ T cells specific for melanocyte differentiation antigens and regression of melanoma metastases." (PMID 18334033, 2008). "We were surprised by the high partial response rate in these 16 patients and postulated that DAB/IL2 may exhibit direct cytotoxic effects against human melanoma cells." (PMID 18334033, 2008). "The results suggest enhanced RRs to the combination of IL-2 and autologous melanoma vaccine." (PMID 14970852, 2004). "The possibility that CC-5013 may boost previously induced immunity is suggested by the fact that five patients with minor responses and static disease had previously been given some form of immunotherapy, such as melanoma peptides or IL-2." (PMID 14997189, 2004). "The aims of the study were to provide an overview of the parameters involved in the mechanisms of immunosuppression in human TIL from melanomas and colorectal carcinomas cultivated for therapeutic purposes and to assess the in vitro effects of exogenous IL-2 on such parameters." (PMID 12610520, 2003).
melanoma (continued). "B7.1+ and B7.2+ melanomas induced proliferation of PBMCs and mRNA for IL-2 and IFN-gamma." (PMID 9652756, 1998). "In this study, several immune parameters which might be involved in mediating antitumour activity have been monitored serially in 15 patients with advanced malignant melanoma or renal cell cancer during treatment with concurrent IL-2 and alpha-IFN." (PMID 7678979, 1993). "Serial thyroid functions studies were carried out in patients with melanoma and renal cell carcinoma treated with interleukin-2 (3 MU m-2 by continuous infusion days 1-4) and interferon alpha-2a (6 MU m-2 subcutaneously on days 1 and 4), both given on alternate weeks." (PMID 2390468, 1990). "Thus, T cell activation indicated by increased IL-2+ cells might be attributed to the inhibition of PD-L1 expression in melanoma cells during co-incubation." (PMID 40574005, 2025). "Furthermore, IL-2 has been the subject of numerous clinical trials in cancer immunotherapy, and recombinant IL-2 has already demonstrated efficacy in stimulating antitumor immunity in several malignancies, including melanoma, renal cell carcinoma and cervical cancer." (PMID 41408300, 2025). "Furthermore, intratumorally injected interleukin 2 (IL-2) and IL-2-containing agents have shown promising response rates and have been used to treat melanoma skin metastases for years.13, –15 However, the number of publications reporting data on patients treated with local IL-2 therapy is limited." (PMID 40171522, 2025). "In NSCLC, down trending IL-2 may signal T-cell dysfunction or regulatory T-cell skewing, suggesting an immunosuppressive milieu or exhaustion phenotype, whilst in melanoma, IL-2 elevations may indicate heightened CD8+ expansion, consistent with its known immunogenicity." (PMID 41020868, 2025). "Until a decade ago the treatment options for melanoma patients were very limited and consisted mainly of highly toxic and poorly effective regimens based on chemotherapy alone or in combination with immunotherapy with high doses of interleukin-2 (IL-2) or interferon alpha (IFNa)." (PMID 39207855, 2024). "Patients in this study generally skewed younger than the average melanoma patient, and all but one patient had received anti-PD-1 therapy prior to study entry, reflecting the typical patient population that would be considered for salvage HD IL-2 therapy in the modern era." (PMID 36845705, 2023). "Thus, IL-2 administration and adoptive transfer of antitumor T cells cultured with IL-2 have represented highly effective therapies in patients with solid human cancers, such as metastatic renal cancer, and melanoma." (PMID 36835413, 2023). "Since the approval of the therapeutic cytokines interleukin-2 and interferon alfa-2 in the 1990s, the development of novel immune checkpoint inhibitors (ICIs), oncolytic virus therapy, and modulators of the tumor microenvironment have given way to a new era in melanoma treatment." (PMID 36831449, 2023). "Moreover, Tabolacci and colleagues demonstrated that AE increased the expression of inflammation-associated factors such as interleukin IL-2, IL-12, GM-CSF and IFN-γ, and showed an immunomodulatory property against different human melanoma cells lines as A375 and SK-MEL-28 cells." (PMID 36768978, 2023). "Thus, we hypothesize that an increment of serum CD25 in melanoma patients who respond to anti-PD-1 therapy could be an indicator of an IL-2-mediated T cell activation, predictive of an effective anti-tumor immune response." (PMID 35361879, 2022). "Consequently, rBCG::IL-2 secreting murine IL-2 has been tested in a mouse model of B16 melanoma." (PMID 35632582, 2022). "Then, melanoma cells expressing a high level of costimulatory molecules directly present a tumor-associated antigen (TAA)–MHC compound to CD8+T cells, stimulating the production of interleukin 2 (IL-2) that leads to their proliferation and differentiation to cytotoxic T cells (CTL)." (PMID 36003368, 2022).